INS (insulin)
Diseases named in the same sentence as INS in open-access papers (continued):
Sharing a sentence is not in itself a finding about the gene and the disease.
Hypokalemia (continued). "The etiologies of hypokalemia include renal losses due to distal renal tubular acidosis and primary hyperaldosteronism, gastrointestinal losses due to diarrhea or vomiting, and intracellular shifts caused by insulin administration or beta-adrenergic activity." (PMID 41191903, 2025). "Nonetheless, hypokalemia causes a reduction in insulin secretion." (PMID 39840160, 2024). "Technically, to treat hypokalemia appropriately, we need to replace fluids that will increase the volume, decrease aldosterone activity, stop potassium loss through urine, and stop ongoing ketosis by starting insulin." (PMID 37605707, 2023). "Moreover, there is a risk of hypokalemia while initiating intravenous insulin therapy due to the aldosterone-related renal potassium loss from RAAS overactivation." (PMID 37102024, 2023). "The main cause of hypokalemia in individuals with DM is the use of high doses of insulin, whether during the treatment of type 1 DM (T1DM) and advanced stages of type 2 (T2DM) or while attempting to correct acute events such as DKA and HHS." (PMID 35334607, 2022). "Furthermore, because angiotensin II stimulates aldosterone secretion, the risk of hypokalemia is raised, necessitating higher supplementation of potassium so that intravenous insulin flows continuously to prevent ketone generation." (PMID 36465737, 2022). "Inpatients with anorexia nervosa presumably have a higher risk of developing hypokalemia because they suffer from severe malnutrition and are refed, in which the insulin surge resulting from glycemia during the refeeding process causes a substantial intracellular uptake of potassium and phosphorus." (PMID 34362446, 2021). "Other potential mechanisms underlying hypokalemia in patients with anorexia nervosa include severe malnutrition and its associated low potassium intake, induction by hypomagnesemia, and surges in insulin that occur during the refeeding process." (PMID 34362446, 2021). "Moreover, the risk is also enhanced by PA through 1) a hypokalemia-induced decrease in initial pancreatic insulin release and 2) a reduction in insulin sensitivity." (PMID 31931803, 2020). "Hypokalemia was associated with lower insulin secretion from pancreatic β-cells in an in vitro study; therefore, the presence of hypokalemia in PA might confound investigations of the link between PA and glucose status." (PMID 31842354, 2019). "Insulin drives potassium into the cell and can cause hypokalemia." (PMID 28167928, 2017). "Another possibility is that using insulin or diuretics caused hypokalemia, which induced VF." (PMID 26981288, 2016). "In addition, potassium redistribution into the intracellular compartment, stimulated by insulin release due to continuous peritoneal glucose infusion was thought to be another important risk factor for hypokalemia." (PMID 24475176, 2014). "Notwithstanding that high doses of insulin may also cause hypokalemia, we deem that the doses this patient received (5 U/hour [58 mU/kg/hour]) are too small to have significantly contributed to his profound and sustained hypokalemia." (PMID 40657235, 2025). "It cannot be forgotten that hypokalemia in older population, might be caused by redistribution of potassium from the intravascular to the extravascular compartment induced by drugs (mostly by insulin in diabetic patients)." (PMID 33830482, 2021). "Chronic hypokalemia and hypomagnesemia impair insulin secretion and insulin sensitivity; and hyperaldosteronism increases insulin resistance; the mechanisms by which they cause insulin secretion and sensitivity, and insulin resistance have been previously published." (PMID 32702863, 2020). "However, the high sK+ at baseline and modified weight‐based dosing of insulin may have decreased the risk of patients developing hypokalemia while receiving treatment." (PMID 32149451, 2020).
Hypokalemia (continued). "However, the biological mechanism behind such an association can be hypothesized based on small clinical trials which have revealed that experimentally-induced hypokalemia (low serum K state) causes impairments in insulin secretion by pancreatic β-cells." (PMID 30169531, 2018). "However, one of the common adverse effects of β2-agonists is hypokalemia (relative risk, 6.07; 95% confidence interval, 4.00 to 9.20), which is due to an increase in uptake of extracellular potassium by promoting insulin secretion in pancreatic islets with β2 adrenoceptor stimulation." (PMID 29492442, 2017). "Glucose-containing fluids are usually avoided in the acute phase to prevent insulin-mediated worsening of hypokalemia." (PMID 41523487, 2025). "Hypokalaemia, in turn, further affects the effect of insulin action, exacerbates metabolic disorders and induces DKA." (PMID 41244780, 2025). "A decision tree model predicted post-CII hypokalemia with 80% accuracy, identifying key predictors such as initial blood glucose and insulin flow rates." (PMID 40546498, 2025). "Treatment strategies range from intravenous potassium supplementation in hypokalemia to calcium gluconate, insulin-glucose infusion, β2-agonists, and renal replacement therapy in hyperkalemia." (PMID 41393542, 2025). "Precipitating factors include high carbohydrate intake, which raises insulin levels, and physical exertion, which increases catecholamine release, both of which stimulate Na+/K+-ATPase activity and exacerbate hypokalemia." (PMID 40630352, 2025). "It is caused by nutritional replenishment following periods of starvation and is marked by a rapid increase in insulin levels, leading to electrolyte imbalances -- hypokalemia, hypophosphatemia, hypomagnesemia -- and decreased levels of thiamine." (PMID 40937209, 2025). "High levels of thyroid hormone, catecholamines and insulin contribute to the development of hypokalemia by preventing the excretion of K from the cell." (PMID 40013235, 2025). "One is the use of dextrose-containing resuscitation fluids, which stimulate insulin release and can aggravate hypokalemia." (PMID 41523487, 2025). "This sort of dietary pattern will often result in hypokalemia due to significant amounts of insulin being secreted in response to the large increase in blood glucose." (PMID 41191903, 2025). "After initial fluid resuscitation with 0.9% sodium chloride, insulin therapy is initiated once serum potassium levels are confirmed to be above 3.3 mEq/L to prevent hypokalemia-induced complications." (PMID 41149081, 2025). "Hypokalemia is a main determinant of decreased insulin secretion in PA, through a mechanism of membrane depolarisation and closure of voltage‐gated calcium channels secondary to the opening of ATP‐sensitive potassium channels." (PMID 40079488, 2025). "For hyperinsulinaemia patients, the primary function of insulin is to facilitate the uptake of potassium from the inside to the outside, and severe intracellular transfer of potassium can lead to hypokalemia." (PMID 40964691, 2025). "Because insulin drives potassium intracellularly and promotes renal excretion, hypokalemia is a common and potentially life-threatening complication of treatment." (PMID 40941597, 2025). "Since insulin facilitates the movement of potassium into muscle cells, insulin therapy should be postponed if hypokalemia is present until potassium levels are normalized." (PMID 40725973, 2025). "Exogenous insulin administration can induce mild hypokalemia by promoting potassium (K+) movement into skeletal muscles and liver cells through increased Na+-K+-ATPase pump activity." (PMID 41149081, 2025). "Following initiation of insulin therapy, the intracellular redistribution of potassium can further precipitate hypokalaemia." (PMID 40919651, 2025). "High rates of hypokalemia and cerebral edema were found, but with lower mortality, showing the effectiveness of subcutaneous insulin for treatment." (PMID 40037551, 2025).
Hypokalemia (continued). "This distinction is important for guiding rapid, targeted interventions, such as potassium supplementation in hypokalemia and calcium or insulin-based therapies in hyperkalemia." (PMID 41393542, 2025). "Hypokalemia (low levels of potassium) is known to impair insulin secretion by hyperpolarizing β-cells and reducing their sensitivity to glucose." (PMID 41156550, 2025). "Electrolyte correction was performed with potassium chloride (KCl) at a concentration of 40 mEq/L and an infusion rate of 80 mL/h to prevent hypokalemia during insulin therapy." (PMID 40941597, 2025). "Although less frequent initially, early recognition and management of hypokalemia are essential, as it can become life-threatening, especially following the initiation of insulin therapy and correction of acidosis." (PMID 40766915, 2025). "Insulin and catecholamines, on the other hand, increase cellular uptake of potassium by activating the Na-K pump, leading to hypokalemia (Unwin, Luft & Shirley, 2011; Ewart & Klip, 1995)." (PMID 39575168, 2024). "Throughout the treatment process, the patient developed hypokalemia due to the use of liposomal AmB and insulin; however, her kidney function remained unaffected, allowing us to continue the treatment regimen." (PMID 39440036, 2024). "Certain diseases can also lead to hypokalemia, such as leukemia, primary hyperaldosteronism, diabetic patients treated with insulin, and patients with diarrhea." (PMID 39575168, 2024). "Catecholamine-induced hypokalemia is thought to be primarily mediated by β2 receptors, with possible potassium influx through the stimulation of the Na+/K+-ATPase in addition to an insulin-mediated effect." (PMID 38792394, 2024). "GS manifests through chronic hypomagnesemia and hypokalemia, which in turn disrupt glucose metabolism due to impaired insulin secretion and sensitivity." (PMID 38333726, 2023). "Hypokalemia secondary to hyperaldosteronism was initially described as a reason for the change in glucose tolerance, by affecting insulin secretion." (PMID 37628857, 2023). "With the current guideline advising against initiating insulin therapy due to fear of cardiac arrhythmia, many patients face another life-threatening acidosis, cardiac arrhythmia due to hypokalemia, and severe neural complications." (PMID 37605707, 2023). "She denied laxative or diuretic abuse, insulin injection, or a history of hypokalemia or cramps in other family members." (PMID 40041278, 2023). "The use of insulin should also lead to careful K level monitoring since insulin can lead to iatrogenic hypokalemia." (PMID 35242575, 2022). "Analogous to diabetic ketoacidosis, the main acute complication of HHS treatment is hypokalemia secondary to insulin administration." (PMID 35334607, 2022). "For instance, in rats, skeletal muscle fibers insulin stimulate the Na/K ATPase during hypokalemia, which is counterbalanced by K-ATP channel activation." (PMID 35884873, 2022). "Acute complications of DM can also evolve with hypokalemia, either during crises or during insulin treatment." (PMID 35334607, 2022). "Hypokalemia leads to both a reduction in pancreatic insulin release and its activity in target cells." (PMID 35334607, 2022). "Our results also confirm that hypokalaemia inhibits the islets β Cell function, especially insulin secretion in the basal state." (PMID 35937831, 2022). "In vitro, hypokalemia prevented the closure of K channels on pancreaticβ-cells and led to decreased insulin secretion." (PMID 36572916, 2022). "As insulin and cerebral edema therapy were initiated, his hypokalemia worsened despite significant IV repletion, eventually leading to ventricular tachycardia and cardiac arrest." (PMID 35494963, 2022). "It is universally known that both hypokalemia and hypomagnesemia can influence insulin secretion and insulin resistance, but the exact mechanisms require further study." (PMID 34348722, 2021).
Hypokalemia (continued). "Disrupted renin-angiotensin-aldosterone system (RAAS) activity and hypokalemia are fundamental aspects of PA; furthermore, aldosterone-induced hypokalemia has been reported to impair glucose tolerance by impeding insulin secretion." (PMID 33967948, 2021). "After intravenous insulin infusion to treat DKA, potassium replacement is required to prevent insulin therapy-induced hypokalemia." (PMID 33392711, 2021). "Severe symptomatic hypokalemia despite aggressive repletion limited the management of DKA with insulin infusion therapy." (PMID 34873512, 2021). "Recent studies have proposed that mechanisms regulating insulin sensitivity in PA patients are mainly dependent on the presence of hypokalemia, whereas the direct effect of excess aldosterone seems to be of minor relevance." (PMID 33967948, 2021). "Previous studies have focused on the direct effects of hypokalemia on insulin secretion and subsequently found that even if the patient's serum potassium level is corrected, the patient's abnormal glucose tolerance has not improved." (PMID 34194493, 2021). "The altered carbohydrate metabolism in patients with hyperaldosteronism was initially attributed to impaired insulin secretion from pancreatic beta cells due to hypokalemia or to a direct inhibitory effect of corticosteroids." (PMID 33967948, 2021). "This is explained by insulin administration and correction of acidosis and hyperosmolarity that drive potassium intracellularly, resulting in hypokalemia; thus, careful monitoring of potassium is an important aspect of management." (PMID 32999787, 2020). "Hyperaldosteronism is associated with impaired carbohydrate metabolism has antecedently been granted to a defective secretion of insulin from pancreatic beta cells owing to hypokalemia, fibrosis, or a direct inhibitory outcome of corticosteroids on beta cells." (PMID 32373073, 2020). "During insulin protocols, transient asymptomatic hypokalemia occurred in 81.8% and in 76.9% of dogs in Group L and in Group R, respectively." (PMID 33195532, 2020). "In the Leuven insulin trial, there were 6% more potassium measurements below 4.0 mmol/l, whilst hypokalaemia < 3.5 mmol/l was successfully avoided in the group targeting tight glucose concentrations 80–110 mg/dl." (PMID 31486927, 2019). "Chronic hypokalemia results in decreased insulin secretion by holding back the closure of ATP-sensitive K + channels and L-type Ca2 + channels on the β cell surface." (PMID 30413979, 2019). "Management involves rehydration, correction of electrolyte derangements; particularly hypokalaemia, administration of insulin, correction of metabolic acidosis, and treatment of precipitants such as infection, pancreatitis, trauma, and myocardial infarction." (PMID 28659865, 2017). "The common side effect of ritodrine is hypokalemia as β2-adrenoceptor stimulation in pancreatic islets by ritodrine promotes insulin secretion to increase uptake of extracellular potassium." (PMID 29492442, 2017). "As insulin therapy induces a shift of potassium from the extracellular to the intracellular space, we expected that the proportion of patients with hypokalemia would increase." (PMID 26100120, 2015). "The current theories regarding the effects of aldosterone on glucose metabolism primarily focus on IR induced by inflammation, oxidative stress, hypokalemia and disturbance of insulin signaling and hepatic gluconeogenesis." (PMID 25582547, 2015). "For instance, hypokalemia which induced by thiazides lowers the insulin secretion and corticosteroids enhance the gluconeogenesis, impair glucose uptake by cells and stimulate alpha cells in the pancreas (hyperglucagonemia)." (PMID 24498320, 2014). "A glucose load to stimulate insulin secretion induced acute hypokalemia (K+2.47±0.6 mmol/l) with reparalysis in only 18% (10/55) of TPP patients." (PMID 23939916, 2013).
Hypokalemia (continued). "Stimulation of cellular potassium uptake is the common mechanism for both insulin-induced hyperpolarization and insulin-induced hypokalemia." (PMID 23319939, 2012). "Semaglutide was discontinued, and insulin was initiated with resolution of hypokalemia." (PMID 40772190, 2025). "Potassium replacement is essential during insulin therapy to avoid hypokalemia." (PMID 41141170, 2025). "Therefore, the subsequent development of hypokalemia reflected an insufficient dose to counteract the characteristic insulin-driven intracellular shift of potassium in DKA." (PMID 41255534, 2025). "Consequently, when insulin therapy was initiated, extracellular potassium enters the cell, the development of hypokalemia was almost an inevitable outcome." (PMID 41255534, 2025). "When using this protocol, the presence of severe hepatic dysfunction on the day after surgery may lead to increased insulin requirements, necessitating careful monitoring for potential complications such as hypokalemia and fat accumulation." (PMID 40400655, 2025). "This is because insulin may promote the intracellular transfer of potassium, thereby exacerbating the preexisting hypokalemia in patients with GS." (PMID 39792715, 2025). "Upon initiation of nutritional therapy, particularly when carbohydrate intake is increased, insulin secretion is restored, promoting the intracellular movement of potassium, phosphorus, and magnesium, leading to hypokalemia, hypophosphatemia, and hypomagnesemia." (PMID 40078418, 2025). "The control of glucocorticoid-induced complications should encompass therapies to stabilize/reverse the CS induced morbidity (e.g., large-spectrum antibiotics for opportunistic infections; spironolactone for hypokalemia; insulin for DM) followed by targeted treatment of hypercortisolism." (PMID 41487740, 2025). "Exogenous insulin injections are critical for sustaining patient survival but may trigger adverse reactions such as hypokalemia (due to insulin-driven intracellular potassium influx) and allergic responses." (PMID 40647154, 2025). "TPP reviews consistently warn that glucose-containing fluids may worsen hypokalemia by stimulating insulin-mediated intracellular potassium shift." (PMID 41523487, 2025). "In one case, the antinatriuretic effect of insulin was prevented by concomitant potassium infusion, suggesting that natriuresis may indirectly depend on insulin-induced hypokalemia." (PMID 39167349, 2024). "On the other hand, considering that chronic hypokalemia can affect insulin secretion and exacerbate glucose abnormalities, the patient’s long-standing low potassium levels, which remained uncorrected, could have compounded the condition." (PMID 39055258, 2024). "Insulin, β-adrenergic catecholamines, and thyroid hormone stimulate the Na+/K+-ATPase pump, which causes a shift in potassium into the cells and results in hypokalemia without affecting the potassium level in the body as a whole." (PMID 39233989, 2024). "Finally, parenteral glucose should be initially avoided in the presence of severe hypokalemia since it induces insulin secretion, which drives potassium into the cells thereby worsening hypokalemia." (PMID 37584686, 2024). "It is significant to also discuss that insulin therapy is not recommended until hypokalemia is corrected to >3.3 mmol/L to decrease risk of arrhythmia and muscle weakness." (PMID 38869331, 2024). "However, the group receiving additional glargine insulin had a higher incidence of hypokalemia than the standard group." (PMID 40433420, 2024). "Glucose infusions should be avoided, as they elevate insulin levels and exacerbate hypokalemia." (PMID 39459472, 2024). "Therefore, potassium replacement is almost always required and should be started together with insulin administration, even if serum potassium levels are normal, so that hypokalaemia is prevented." (PMID 37568965, 2023).